SOX6 (SRY-box transcription factor 6)
Diseases named in the same sentence as SOX6 in open-access papers (continued):
Sharing a sentence is not in itself a finding about the gene and the disease.
diabetes (6 papers, 2008 to 2025). "So, Sox6 could be a potential therapeutic target to design better drug to treat diabetes and associated complications." (PMID 33230925, 2020). "Further experiments to explore the role of SOX6 and its downstream targets in the pathogenesis of IHL in diabetes are warranted to establish SOX6 as an independent regulator of angiogenesis, in vivo." (PMID 40640841, 2025). "In this study, the role of miR-499-5p/SOX6 axis in diabetes/ischemia-impaired hindlimb injury recovery was limited in young db/db mice." (PMID 40640841, 2025). "SKMC-sEV-mediated transfer of myo-miR-499-5p and subsequent suppression of SOX6 plays a critical role in diabetes-impaired neovascularization in IHL of db/db mice." (PMID 40640841, 2025). "Our findings suggest that miR-499-5p impairs EC function in diabetes by SOX6-regulated suppression of pro-angiogenic factors." (PMID 40640841, 2025). "In this review, we focus on the function of Sox6 in cardiovascular diseases, hypertension, and diabetes and related conditions." (PMID 33230925, 2020). "Therefore, it may be worthy for future studies to explore if miR-499-5p/SOX6 axis in the pathogenesis of ischemic hindlimb injury in diabetes is age dependent." (PMID 40640841, 2025). "Hypertensive and diabetes complications stratified analyses showed that the link between SOX6 SNPs and the KBD risk was not markedly impacted by whether or not the patient had hypertension or diabetes." (PMID 38205152, 2024). "These include genes with known function in islets and diabetes such as ATP6V1H, SOX6, SOCS1 and STX1145–48." (PMID 31123324, 2019). "However, expression of SOX6 in ECs and a role of SOX6 in EC function with respect to diabetes has never been studied." (PMID 40640841, 2025).
endometrial cancer (5 papers, 2021 to 2025). Primary or metastatic malignant neoplasm involving the endometrium (mucous membrane that lines the endometrial cavity). "In endometrial cancer, UBE2S promotes the proliferation and migration of endometrial cancer cells through SOX6/β-Catenin signaling." (PMID 36611207, 2023). "The ectopic expression of UBE2S promoted cell proliferation and migration via regulating SOX6/β-Catenin in endometrial cancer (EMC)." (PMID 34535173, 2021). "In addition, other studies have shown that UBE2S could inhibit the tumor progression of endometrial cancer through the SOX6/β-Catenin signaling pathway." (PMID 35658829, 2022).
insulinoma (5 papers, 2008 to 2013). "Glucose-regulated interactions between Hdac1/2, Pdx1 and/or Sox6 have been suggested to control insulin gene expression in mouse insulinoma cell lines." (PMID 18687323, 2008). "It has been reported that Sox6 inhibits cyclin D1 expression by interacting with β-catenin and HDAC1 in insulinoma INS-1E and NIH-3T3 cells and that down-regulation of cyclin D1 is important for cell cycle exit." (PMID 24040263, 2013). "In contrast, a previous report showed that SOX6 overexpression decreased cell proliferation in INS-1E insulinoma cells and NIH3T3 cells, indicating the possibility that Sox6 may regulate cell proliferation in a cell type-dependent manner." (PMID 24066135, 2013).
lung adenocarcinoma (5 papers, 2018 to 2024). A carcinoma that arises from the lung and is characterized by the presence of malignant glandular epithelial cells. "Univariate and multivariate analyses revealed that the expression of SOX6 is significantly associated with patient disease‐related survival and is an independent prognostic factor for lung adenocarcinoma." (PMID 31729835, 2020). "To clarify the mechanism of SOX6 in lung adenocarcinoma, we carried out cell cycle and immunoblotting assays." (PMID 31729835, 2020). "To investigate the clinical significance of down‐regulation of SOX6 expression in lung adenocarcinoma, we retrospectively analyzed the clinical data of 145 patients with lung adenocarcinoma." (PMID 31729835, 2020). "We showed that the expression of SOX6 in lung adenocarcinoma tissues was down‐regulated at both the protein and the mRNA level." (PMID 31729835, 2020). "Here, we investigated the expression of SOX6 in lung adenocarcinoma and its role and potential mechanism of action in tumor development." (PMID 31729835, 2020). "In contrast, the levels of SOX6 were lower in lung adenocarcinomas (sections with overall scores ≥ 4, 57/145, 39%)." (PMID 31729835, 2020). "To assess the relationship between the expression of SOX6 and the clinicopathological features and prognosis of patients with lung adenocarcinoma, we compared SOX6 expression in the 145 lung adenocarcinomas with clinicopathological characteristics." (PMID 31729835, 2020). "We further examined the effect of SOX6 expression on the invasiveness of lung adenocarcinoma cells using wound healing and Transwell assays." (PMID 31729835, 2020). "We found that lung adenocarcinoma cells stably transfected with SOX6 showed increased numbers of cells in G1 phase, indicating that SOX6 negatively regulates G1 phase transition in lung adenocarcinoma cells." (PMID 31729835, 2020). "SOX6 suppresses the cell cycle of lung adenocarcinoma by regulating cyclin D1, which indicated miR-1269a might be involved in radiation sensitivity." (PMID 34504628, 2021). "Here, we report that SOX6 expression is frequently down‐regulated in lung adenocarcinoma tissues." (PMID 31729835, 2020). "We found that Sry‐related high‐mobility group box6 (SOX6) may be a tumor suppressor in lung adenocarcinoma, and prognosis of patients with lung adenocarcinoma with low SOX6 expression is poor." (PMID 31729835, 2020). "We demonstrated that SOX6 reduced the expression of β‐catenin in a lung adenocarcinoma cell line, suggesting that the tumor suppressor function of SOX6 may be associated with this signaling pathway." (PMID 31729835, 2020). "Our study suggests that SOX6 may be a tumor suppressor in lung adenocarcinoma, and our results show that the prognosis of patients with lung adenocarcinoma with low SOX6 expression is poor." (PMID 31729835, 2020). "In this study, we found that SOX6 was down‐regulated in patients with lung adenocarcinoma, and in vitro cell experiments indicated that SOX6 inhibits the proliferation, migration and invasion of lung adenocarcinoma cells; thus, SOX6 may possibly function as a tumor suppressor." (PMID 31729835, 2020).
lung adenocarcinoma (continued). "SOX6, as a new immunohistochemical marker of MM, has similar sensitivity to CR and D240 in differentiating epithelial MPM from lung adenocarcinoma, but it has better specificity." (PMID 38938650, 2024). "Western blot results further confirmed that the expression of SOX6 protein was down‐regulated in lung adenocarcinoma tissues compared with adjacent nontumor tissues." (PMID 31729835, 2020). "We examined SOX6 mRNA in 30 pairs of adjacent nontumor tissues and lung adenocarcinomas, and detected significantly higher levels in the nontumor tissues (22/30, 73%); the difference in SOX6 mRNA levels was statistically significant (P < 0.001)." (PMID 31729835, 2020). "Immunohistochemical analysis of paraffin‐embedded sections from 145 pairs of lung adenocarcinomas and adjacent nontumor tissues revealed that SOX6 was frequently expressed in nontumor tissues (sections with overall scores ≥ 4, 132/145, 91.3%)." (PMID 31729835, 2020). "No studies have explored the role of SOX6 in lung cancer; thus, our current research provides some preliminary data in this area and suggests a new direction for further exploration of new targets in lung adenocarcinoma." (PMID 31729835, 2020).
ovarian carcinoma (5 papers, 2020 to 2025). A malignant neoplasm originating from the surface ovarian epithelium. "Through up-regulating FBXO2, SOX6 would promote ovarian cancer progression by inhibiting cell apoptosis." (PMID 40866912, 2025). "SOX6 has not been reported in MMD; however, a study indicated that SOX6 may inhibit the proliferation and invasion of ovarian cancer cells and tumor cell-induced angiogenesis." (PMID 35368875, 2022).
pancreatic cancer (5 papers, 2018 to 2024). "In pancreatic cancer, SOX6 downregulates TWIST1 by recruiting HDAC1 to the TWIST1 promoter, which inhibits pancreatic cancer metastasis." (PMID 38331879, 2024). "Numerous studies have reported that SOX‐6 expression was deregulated in ESCC, oral squamous cell cancer, and pancreatic cancer." (PMID 35499218, 2022).
Parkinson disease (5 papers, 2018 to 2025). A progressive degenerative disorder of the central nervous system characterized by loss of dopamine producing neurons in the substantia nigra and the presence of Lewy bodies in the substantia nigra and locus coeruleus. "Within the midbrain, SOX6 is similarly important for the generation of substantia nigra dopamine neurons, and lower levels of SOX6 accompany the loss of these neurons in patients with Parkinson’s disease." (PMID 29031500, 2018). "It is worth noting that SOX6 is a marker of DA neurons in the substantia nigra, the brain region most severely affected by Parkinson’s disease." (PMID 38672099, 2024). "DA neurons of the human adult substantia nigra pars compacta (SNc), corresponding to the ventral A9 region, are marked by the expression of SOX6 and AGTR1, express higher levels of PD-causative genes and have been shown to be more vulnerable to Parkinson’s disease (PD)." (PMID 41279649, 2025). "AEP is subsequently activated by α‐Syn fibrils in the SNpc, leading to cleavage of Sox6 and ALDH1A1 in SNpc DA neurons, contributing to the vulnerability of dopaminergic neurons in Parkinson's disease." (PMID 39573918, 2025).
anemia (4 papers, 2010 to 2024). A reduction in the number of red blood cells, the amount of hemoglobin, and/or the volume of packed red blood cells. "Developing erythroid cells thus became abnormal before the reduced lifespan or other defects of mutant RBCs became consequential, indicating that impaired erythroid cell maturation is a primary cause of anemia upon Sox6 inactivation." (PMID 20711497, 2010). "It is very likely that erythroid defects are the cause of this anemia since wild-type adult mice strongly express Sox6 in erythropoietic tissues and since Sox6fl/flErGFPCre mice inactivate Sox6 only in erythroid cells." (PMID 20711497, 2010). "In addition to Epo treatments widely used to generate an adequate burst of early erythroid cells in patients with various anemia-causing conditions, one should thus also consider targeting Sox6 to ensure timely maturation and release, as well as long life of newly generated red blood cells." (PMID 20711497, 2010). "Here, we reactivated γ-globin expression by downregulating SOX6 to alleviate anemia in the β-thalassemia patients." (PMID 29333458, 2017). "These defects are accompanied with a reduced survival of Sox6−/− red blood cells, resulting in a compensated anemia." (PMID 29074889, 2017). "We demonstrated that Sox6 significantly contributes to ensuring efficient basal erythropoiesis by showing that Sox6fl/flErGFPCre adult mice had compensated anemia." (PMID 20711497, 2010). "This function of Sox6, however, is probably largely compensated for in mutant mice subjected to acute anemia by the very high increase in sEpo level." (PMID 20711497, 2010). "Sox6 is dispensable to generate the surge in sEpo level and the Epo-mediated early response to acute anemia, which includes spleen enlargement and massive production of proerythroblasts and early erythroblasts." (PMID 20711497, 2010). "Sox6 thus critically participates in the erythropoietic burst generated in response to acute anemia." (PMID 20711497, 2010). "As a consequence, Sox6−/− RBCs have a reduced survival, finally resulting in a compensated anemia." (PMID 29074889, 2017). "We next tested whether the abnormal development of erythroid cells in Sox6fl/flErGFPCre mice was a direct consequence of Sox6 inactivation or was due to anemia-induced stress erythropoiesis as a result of reduced survival or malfunction of RBCs." (PMID 20711497, 2010). "Further supporting this mechanism, we showed that Sox6fl/flErGFPCre mice had erythroid cell defects and decreased RBC life span, and that Sox6fl/flCaggCreER adult mice, which inactivated Sox6 only upon tamoxifen injection, developed erythroblast defects before anemia." (PMID 20711497, 2010). "To better understand how Sox6 controls erythroid cell development, we screened gene expression microarrays with bone marrow and spleen RNA from Sox6fl/fl and Sox6fl/flErGFPCre littermates at 3 months of age under physiological conditions and 4 days after induction of acute anemia by PHZ." (PMID 20711497, 2010). "Sox6fl/flErGFPCre adult mice, which lacked Sox6 in erythroid cells, exhibited compensated anemia, erythroid cell developmental defects, and anisocytotic, short-lived red cells under physiological conditions, proving that Sox6 promotes basal erythropoiesis." (PMID 20711497, 2010). "We concluded that adult mice maintained under physiological conditions but lacking Sox6 in erythroid cells exhibited compensated anemia, with underdevelopment of proerythroblasts, impaired maturation of erythroblasts and reticulocytes, and decreased survival of RBCs." (PMID 20711497, 2010).
chondrodysplasia (4 papers, 2014 to 2022). "Inactivation of SOX5 leads to minor defects in cartilage and skeletogenesis in mice, whereas SOX5/SOX6 double knockouts have severe chondrodysplasia." (PMID 30261039, 2018). "Although single null mice of Sox5 or Sox6 showed mild chondrodysplasia, double-null mice of Sox5 and Sox6 exhibit severe chondrodysplasia." (PMID 25546433, 2014). "Although double knockout of Sox5 and Sox6 leads to severe chondrodysplasia, lacking either of them has modest skeletal defects, suggestive of genetic redundancy." (PMID 36289842, 2022).
craniosynostosis (4 papers, 2011 to 2023). Craniosynostosis is defined as the premature fusion of one or more cranial sutures leading to secondary distortion of skull shape resulting in skull deformities with a variable presentation. "While our functional studies focused on genes uniquely associated with variation in skull BMD, there are plenty of genes implicated in craniosynostosis (e.g., EN1, RUNX2, SOX6, BMP2, JAG1, LRP5, IDUA30,44,47,48) across the whole set of identified BMD loci." (PMID 37402774, 2023). "Sox6 is known to be important for proper cartilage formation, and one child with craniosynostosis (premature fusion of the cranial sutures) and facial dysmorphisms has been shown to carry a heterozygous mutation in SOX6." (PMID 21876820, 2011).
diabetic nephropathy (4 papers, 2020 to 2024). "Sox6 has been implicated in diabetic nephropathy, adipogenesis, cardiomyopathy, inflammatory bowel disease, and cancer." (PMID 33230925, 2020). "This recruitment accelerates the progression of diabetic nephropathy by epigenetically repressing SRY-box transcription factor 6 (SOX6)." (PMID 39595187, 2024). "For example, miR-342 was reported to inhibit renal interstitial fibrosis and renal mesangial cell apoptosis in mice with diabetic nephropathy by downregulating the expression of SRY-box 6 (SOX6)." (PMID 38204237, 2024). "For instance, in diabetic nephropathy, miR-203a-3p regulates SOX6 to inhibit the inflammatory response of mesangial cells." (PMID 38095638, 2023). "In this minireview, we present recent developments related to the transcription factor Sox6, which is involved in a number of diseases such as diabetic nephropathy, adipogenesis, cardiomyopathy, inflammatory bowel disease, and cancer." (PMID 33230925, 2020). "Using a DKD model, and mouse renal mesangial cells (MCs), Jiang and colleagues studied the miRNA‐342 mediated regulation of Sox6 and impacts on interstitial fibrosis during diabetic nephropathy." (PMID 33230925, 2020).
Ewing sarcoma (4 papers, 2022 to 2025). A small round cell tumor that lacks morphologic, immunohistochemical, and electron microscopic evidence of neuroectodermal differentiation. "Transcription factor SOX6 (SRY-Box Transcription factor 6) is highly expressed in Ewing’s sarcoma cells that display a highly proliferative phenotype." (PMID 35329989, 2022). "The three MTFs (POU3F2 & SOX6 & IKZF2) colocalised in 50% of top 100 Ewing sarcoma SEs." (PMID 41444391, 2025). "Finally, we apply the power of this assay to determine the function of the EWSR1::FLI1 fusion oncogene and its transcriptional target SOX6 as plasticity factors that enhance the adaptive capacity of metastatic Ewing sarcoma." (PMID 40501949, 2025). "Data 5), we selected six MTFs (TCF12, SOX6, POU3F1, POU3F2, NKX2-2, and IKZF2) as putative members of the Ewing sarcoma CRC, based on fulfilling at least two out of these three criteria." (PMID 41444391, 2025).
heart failure (4 papers, 2011 to 2025). Inability of the heart to pump blood at an adequate rate to meet tissue metabolic requirements. "Since the Sox6 KO phenotypes reported here have relevance to muscle degenerative diseases as well as heart failure, uncovering the many functions of Sox6 in muscle development will likely contribute to the understanding of mechanisms of human muscular diseases." (PMID 21985497, 2011). "A study has shown that miR-342-3p can target and downregulate the expression of SOX6 and TFEB, thereby inhibiting myocardial cell apoptosis and autophagy, and exerting a protective effect on myocardial cells in mice with heart failure induced by myocardial infarction." (PMID 40997050, 2025).
Hypertension (4 papers, 2012 to 2025). The presence of chronic increased pressure in the systemic arterial system. "GWAS studies associate Sox6 SNPs with human hypertension across the ethnicities and imply great potential of functional studies for Sox6 in hypertensive animal models to discern the Sox6 function and establish molecular pathway/s in hypertension." (PMID 33230925, 2020). "In addition to the function of Sox6 in the development, and cardiovascular diseases, Sox6 has also been associated with human hypertension." (PMID 33230925, 2020). "By performing follow‐up analysis in additional 59,349 individuals, they confirmed the associations of Sox6 SNPs in one of the blood pressure traits such as DB, SBP, MAP, PP, and hypertension." (PMID 33230925, 2020). "Moreover, this work reveals an original aldosterone-dependent inhibition of miR-208a in hypertension, resulting in the inhibition of β-myosin heavy chain expression through the induction of its transcriptional repressor Sox6." (PMID 22666483, 2012).